NOS2 (nitric oxide synthase 2)
Diseases named in the same sentence as NOS2 in open-access papers (continued):
Sharing a sentence is not in itself a finding about the gene and the disease.
infection (continued). "Interestingly, NOS2 gene involved in controlling infection of a closely related mycobacteria, M. tuberculosis, was significantly induced (>100 fold) in both vaccine groups, suggesting an important role of this gene in adaptive immune responses following immunization with LAV or inactivated vaccine." (PMID 30323794, 2018). "Therefore, understanding the molecular mechanisms that lead to Nos2 activation may allow the development of therapeutic strategies aiming to increase its activation in case of infections or reduce its activation in inflammatory pathologies." (PMID 28150715, 2017). "However, the intraphagosomal NOS2 localization is not seen following infection with M. bovis (BCG-associated var)." (PMID 29085351, 2017). "Moreover, when incubated with macrophages in vitro L. infantum IMT-151 led to the early induction of Arginase rather than Nos2 expression, although in vivo a significant induction of Nos2 in the liver could be seen at 60 days post-infection." (PMID 26684322, 2015). "However, in the absence of NOS2, animals die with a slower kinetics than IFN-γ−/− mice, suggesting that mechanisms in addition to NOS2-mediated NO production may be relevant for IFN-γ-mediated host protection to infection." (PMID 22206036, 2011). "Furthermore, untreated nos2/gp91−/− mice were not more susceptible to SchuS4 infection compared to untreated wild type mice." (PMID 20523903, 2010). "Histopathology and inflammatory genes (Nos2, Il-1β, Tnf-α, and Cxcl1) were elevated and persisted in the large intestine of muMT mice compared with WT mice during chronic ETBF infection." (PMID 38203534, 2023). "High NOS2 mRNA levels and NOS enzymatic activity have been detected in rat brains infected with the CVS-24 strain of RABV 3 days after infection along with the onset of clinical signs of disease." (PMID 37692167, 2023). "Our results revealed that the upregulation of lyst transcription after infection is due to effector secretion of C. burnetii and LYST inhibit the intracellular replication of C. burnetii by reducing the size of CCVs and inducing nos2 expression." (PMID 38282619, 2023). "Nitric oxide synthase 2 (NOS2) or inducible NOS, is also involved in the inflammatory responses that occur after infection or tissue injury." (PMID 35897044, 2022). "The other isoform is inducible NO synthase (iNOS/NOS2), which is activated in response to cytokines and specific substances related to infection like endotoxins." (PMID 35884830, 2022). "Once the adaptive response was established after 30 days of infection, we observed a significant decrease in ΔcydA lung CFU compared to H37Rv in wildtype, Nos2−/−, and Cybb−/− mice." (PMID 34320028, 2021). "The genes, Ccl2, Ccl20, Csf1, Cx3cl1, Cxcl1, Cxcl3, Il6, Birc3, Map3k8, Nos2, Nfkb2, Tnfrsf1b, and Vcam1, played core roles in a PPI network, and interacted closely with other ones in the infection." (PMID 33042984, 2020). "In contrast, NOS2 and IFN-γ mRNA levels in WT mice at 24 weeks post infection were remarkably up-regulated than in naïve mice, while the levels in MRP14KO mice were significantly lower compared to WT mice." (PMID 31961866, 2020). "At initial stages of infection, the Mtb pathogen takes advantage of ARG1 activity by limiting macrophage immunity via competition with iNOS/NOS2." (PMID 32903583, 2020). "Three weeks after infection, MAP was most prevalently found in macrophages that express NOS2 and thus produce NO." (PMID 32408806, 2020). "Henceforth, in disulfiram-treated mice, the level of NOS2 (M2 polarizing factor) was elevated compared to those of the doxycycline-treated and PBS infected groups at day 21 or day 28 post infection." (PMID 32971817, 2020). "At 8 weeks post-infection, expression of IL10, NOS2, and SMAD7 was significantly up-regulated in the Fe-supplemented animals." (PMID 31382404, 2019).
infection (continued). "We observed significantly increased transcript levels of NOS2, CXCL9, and CXCL10 beginning at day 5 post-infection in DCs isolated from H99γ infected mice compared to DCs from H99 infected mice." (PMID 31273203, 2019). "Together, our data for the first time clearly demonstrate that the induction of Nos2- and Arg1-expressing M-MDSC provides an immune escape mechanism that supports infection and pathology by virulent M. avium subspecies." (PMID 30386330, 2018). "By qPCR, we detected greater Nos2 mRNA expression in the spleens of the A2AR−/− mice than in the WT group at both the fourth and sixth weeks post infection." (PMID 28775724, 2017). "Infection with La-arg- reduces the levels of CAT2B, CAT1 and ARG1 and allows the expression of NOS2 and NO production in BALB/c macrophages, thereby reducing the infectivity." (PMID 29379478, 2017). "The Nos2 mRNA expression and the NOS2 protein levels in La-arg− + ARG were similar to La-WT, at 4 and 48 h of infection." (PMID 28276497, 2017). "The amounts of cytokines, Tnfα Interleukin 6 (Il6) and Ifnγ in the sera increased significantly by day 4 post infection in both C57BL/6 and Nos2-/- mice." (PMID 26029930, 2015). "There was an increase in NOS2 mRNA expression in spleen starting on day 3 after DENV-3 inoculation and rising rapidly on days 5 and 7 post infection." (PMID 22666512, 2012). "We observed that the level of expression of nitric oxide synthase (Nos2), a marker of macrophage activation, was significantly higher in CDC1551-infected BMM, compared to infection by HN878." (PMID 22280836, 2012). "It has recently been shown that Nos2a, the zebrafish homolog of NOS2, is also required for the expansion of hematopoietic stem cells and progenitor cells during infection, leading to increased numbers of the required immune cells." (PMID 22811714, 2012). "There was no Nos2 gene upregulation in Salmonella-infected RAW264.7 at 1 h post-infection, but pretreatment with either viable or heat-killed KUNN19-2 significantly enhanced Nos2 expression in macrophages." (PMID 40076451, 2025). "Pretreatment of UPEC-infected murine macrophage RAW264.7 cells with viable AC5 (multiplicity of infection, MOI = 1) for 24 hours enhanced macrophage-killing activity and increased proinflammatory (Nos2, Il6, and Tnfa) and anti-inflammatory (Il10) gene expression." (PMID 39091675, 2024). "We found that infection of neonatal mouse cardiomyocytes with both T. cruzi isolates with different virulence degrees, followed by stimulation with TNF-α + IFN-γ, led to a significant decrease in NOS2 expression, which was similar in magnitude." (PMID 39452749, 2024). "NOS2 expression was not increased, whereas STm WT infection significantly increased the expression levels of Arg-1 and Arg-2." (PMID 39102375, 2024). "To further explore the relationship between cellular respiration and efflux activity of persisters during infection, we extracted active non-growers of the WT, ΔsucB, and ΔacrB strains after 26 hours of cefotaxime treatment inside Nos2-/- macrophages." (PMID 38421944, 2024). "In the case of BMMΦ, the infection with T. cruzi and stimulation with TNF-α + IFN-γ diminished NO2 protein presence, and interestingly, the infection with the QRO isolate diminished NOS2 protein presence to a major extent as compared to the infection with the CI2 isolate." (PMID 39452749, 2024). "Our data indicates the augment of Nos2 expression by L-arginine-deprivation and putrescine supplementation during infection without corresponding with NO production." (PMID 37000792, 2023). "Since Nos2 was a specific marker for this cell group, a comparison between the infected and non-infected livers showed a significant increase in Nos2+ cells after infection." (PMID 37638012, 2023). "Inducible NO synthase encoded by NOS2 is a cytoplasmic protein and is absent in resting cells, but is rapidly produced in response to stimuli, such as infections and cytokines." (PMID 36855359, 2023).
infection (continued). "Unexpectedly, L-arginine deprivation increased Nos2 levels at 4 h of infection without affecting NO production." (PMID 37000792, 2023). "Genes such as TNFα, IL10, TLR15, IL8L1 (CXCLi1), IL8L2 (CXCLi2), NOS2, ACOD1 and PTGS2 were upregulated with infection and microbiota, suggesting that macrophages may largely participate in the pro-inflammatory response described in caecal tissues." (PMID 38098020, 2023). "After infection with C. burnetii, the L-NMMA-treated THP-1 cells were significantly enhanced in intracellular C. burnetii load compared to that of controls, suggesting that the expression of nos2 inhibits the intracellular proliferation of C. burnetii." (PMID 38282619, 2023). "Without these pyroptotic proteins, mice still express Nos2 and generate NO, but this antibacterial mechanism fails to clear the infection." (PMID 37865673, 2023). "Despite upregulation of M1-promoting cytokines (Ifng, Il1b) throughout the infection, inducible NO synthase (Nos2), the effector molecule of M1 polarization, exhibited none or negligible changes in expression." (PMID 35120185, 2022). "Infection of macrophages derived from IRF3-KO mice with L. monocytogenes failed to induce NOS2 expression observed in W.T. macrophages." (PMID 36010574, 2022). "Our data are consistent with a recent study that conducted immunological transcriptional profiling of mouse cecal tissue in response to WT or non-toxigenic Cd11 and found increased Nos2 expression but not Arg1 in response to WT infection." (PMID 34992297, 2022). "However, other proteins such as ISG15, Nitric Oxide Synthase 2 (NOS2), IL1-β and IFIT1 were similarly altered in both conditions upon infection." (PMID 36131943, 2022). "The functional inhibition of miR-294 and miR-301b increased the expression of Nos2 levels slightly at 4 h of infection, which was not significant." (PMID 35202090, 2022). "Additional genes that were downregulated after treatment with 1,25(OH)2D3 were CCL5 and NOS2, the gene for iNOS, both of which showed a significant decrease (P < 0.05) across all groups regardless of infection status." (PMID 35211544, 2022). "Mincle-/- cells also produced less Nos2, Tnfa, Il27, and Cxcl9 than WT cells upon infection, but the reduction did not meet statistical significance under the tested infection doses and time." (PMID 34320039, 2021). "Notably, the majority chemokine ligand, which induced cells of the immune system to enter the site of infection, CCL-2, CD80 and CD68 of TAMs, IRF5 and NOS2 of M1, CD163 and MS4A4A of M2 were strongly related to JAK1 expression in LUAD (all P value < 0.0001)." (PMID 34587898, 2021). "To directly test this hypothesis, we compared the liver infection loads of Ctrl and RKV-supplemented Nos2−/− mice, which cannot produce NO via iNOS." (PMID 33294789, 2020). "While NOS-2 levels elevated at day 21 and MIP-2 levels reduced at day 28 post infection." (PMID 32971817, 2020). "The production of NO by NOS2 apparently restricted MAP growth and disease since the absence of Nos2 in recombinant mice resulted in a higher bacterial load and increased pathology 5 weeks post infection." (PMID 32408806, 2020). "Consequently, infection of macrophages with the Mtb Ppe2 deletion mutant and Msme overexpressing Mtb PPE2 result in increased or decreased NOS2 protein expression." (PMID 33194845, 2020). "On the other hand, the higher expression of NOS2 deviates the use of L-arginine to produce NO in infected macrophages, promoting parasite killing, and enabling resistance to infection in C57BL/6 mice infection." (PMID 31835767, 2019). "As with the investigated pro-inflammatory cytokines, NOS2 mRNA levels were significantly higher, with on average 2.7 times more NOS2 mRNA (p < 0.001) being detected, during G18 infection in the absence of IL10." (PMID 31527895, 2019). "Nos2 protein levels were not significantly affected although mean levels were increased on days 6 and 8 post-infection." (PMID 31299982, 2019).
infection (continued). "While there was no induction of Nos2 in spleen macrophages upon infection of hamsters with L. donovani, Nos2 expression, nevertheless, contributed to the parasite-containment in the spleen of L. donovani and L. infantum-infected mice." (PMID 29520262, 2018). "Together, after infection with T. cruzi the expression of NOS2 was not impaired in the presence of high IL-13 concentrations." (PMID 30555475, 2018). "In line with previous studies, our data confirm that the absence of Nos2 in MAA-infections improved bacterial clearance." (PMID 30386330, 2018). "Notably, let-7e inhibition regulated Arg1 and Nos2 expression during infection, corroborating the importance of the TLR signaling cascade in the mechanism regulating Arg1 and Nos2 expression at the transcriptional level." (PMID 30555476, 2018). "Inflammatory response genes, such as NOS2, IL6 and TNFRSF1B, were up-regulated while some positive regulation of inflammatory response genes, such as TLR3, STAT5 and LRRC32, were also elevated post-infection with IBDV." (PMID 28486945, 2017). "It was also observed that electroretinographical changes seems not to be associated to retinal inflammation since no increase on TNF levels or NOS-2 expression were observed in the retinal tissue at 7 days post-infection." (PMID 29096633, 2017). "After 4 h of infection with La-WT L. (L.)amazonensis, the host Nos2 expression was not altered, but we observed up-regulated expression of host Arg1 mRNA." (PMID 28276497, 2017). "On the other hand, the resistance to infection is associated with Th1 response, with the production of TNF, IL-12 and IFN-γ cytokines and induction of NOS2 expression with consequent NO production resulting in a M1 macrophage functional state, as observed in C57BL/6 mice infection." (PMID 29379478, 2017). "Although infection with C. burnetii increase the expression of Nos2 there was no production of nitrites by these cells, which agrees with previous results using human." (PMID 26366725, 2015). "NOS2-/- BMM exhibited similar ferritin protein profile changes to those of WT BMM post infection, demonstrating that NO is not involved in the regulation of ferritin by M. avium." (PMID 24349383, 2013). "Importantly, the expression of several key genes essential for the antimicrobial activities of macrophages, including NOS2 and CAP18, were upregulated in CDC1551-infected rabbit lungs as early as 2 weeks post-infection." (PMID 23448601, 2013). "At the emergence of ulceration in non-treated mice (day 21 post-infection), larger areas with clumps of bacilli were observed, and, again, NOS2 staining was absent, as well as in the peripheral areas." (PMID 22393444, 2012). "Furthermore, expression of several key host defense genes, including cytokines (TNFα and IL6) and bactericidal molecules, such as defensin-4 (NP4), NOS2, NOX1 and ICAM1, peaked only at 8 and/or 12 weeks post-infection." (PMID 22645653, 2011). "As early as 6 hours after infection, the expression of Arg1 and Fizz1 was detected in the infected lungs when compared to uninfected controls but no induction of NOS2 was noticed." (PMID 21246055, 2011). "Therefore, NOS2-derived NO production is driven by IFN-γ and is essential for host protection during DENV primary infection." (PMID 22206036, 2011). "The expression of inducible nitric oxide synthase (NOS2) was strongly induced during reinfection but not during primary infection." (PMID 21414188, 2011). "Finally, we show that IFN-γ controls expression of NOS2 and NO production after DENV-2 infection and that NO production is crucial for resistance of the murine host to infection with DENV." (PMID 22206036, 2011). "Although some controversy still persists, in vivo data demonstrate that non-rodent species display functional NOS-2 expression after infection with a wide array of pathogens." (PMID 17686182, 2007). "Consistently, I-17 induced NOS2 mRNA with or without infection with L. amazonensis." (PMID 38392842, 2024).
infection (continued). "The heat map allowed us to visualize the response obtained upon putrescine supplementation with or without L-arginine concomitant to infection, characterized by induction of Nos2 and Arg2, and the response to spermidine supplementation at 4h, with downregulation of Mcp-1 and IL1b." (PMID 37000792, 2023). "Curiously, Nos2 levels negatively correlated with the percentage of NO-producing cells and median of fluorescence (MFI) of NO production, suggesting that infection with Leishmania negatively impacts NO production during arg+ or arg- conditions at the first hours of infection." (PMID 37000792, 2023). "Curiously, the increase in the frequency of DAF-FM+ cells during 24h macrophage infection induced by arg+/spm+ negative correlates with Nos2 levels (Corr -0.925, p < 0.05) and Nos2 levels negatively correlate with NO production per cell (MFI; Corr -0.929, p < 0.05)." (PMID 37000792, 2023). "In separate (WT or Tox−) infections, we could not rule out potential alterations in host immune response due to the Nos2 genotype." (PMID 34992297, 2022). "Although the levels of Cat1/Slc7a12 Cat2/Slc7a22 Arg1, and Odc1 did not behave as expected during infection, increased levels of the Arg2 transcript level were not reflected by the increased competition of cytoplasmatic arginine with NOS2 because of its mitochondrial localization." (PMID 35202090, 2022). "The LPS promoted a similar increase of Nos2 at 4 h, but it was not modified during infection." (PMID 35202090, 2022). "Since we chose miRNAs with the predicted binding site of the 3′UTR of the target genes Nos2, Cat2/Slc7a2, and Cat1/Slc7a1 and because the genes were increased during LPS stimulation but not during infection, it was expected that inhibition would increase the expression of the target mRNAs." (PMID 35202090, 2022). "In conclusion, the gene-expression signature predominant in livers of BALB/c mice 10 days after infection with L. infantum is characterized by the overrepresentation of IL12-mediated signaling events (FDR=0.003) with the strong upregulation of Il12rb2, Ifng, Nos2, Il12rb1, and Il12b." (PMID 34281214, 2021). "Thus, our results indicate that the enhanced NOS2 expression, NO production and the inflammatory profile promoted by HIF-1α may support the control of B. abortus during the early phase of infection." (PMID 33989349, 2021). "The authors found that infection by S. enterica typhimurium induces the expression of HO-1 in liver tissue in vivo and macrophages in vitro and this response was found to be dependent on the formation of the GMP derivative 8-nitro-cGMP product of NOS2-mediated NO generation." (PMID 33266044, 2020). "Importantly, we found upregulation of Nos2 mRNA expression in the brain of wt but not C5ar1−/− mice during early infection in comparison to the naïve state." (PMID 32733463, 2020). "However, NOS2 mRNA levels were not significantly affected during AF2122/97 infection by the absence of IL10." (PMID 31527895, 2019). "Furthermore, nitric oxide (NO) production was modulated by IL10 during AF2122/97 infection, but not at the nitric oxide synthase 2 (NOS2) mRNA level, as observed during G18 infection." (PMID 31527895, 2019). "Moreover, while brain cortex of P. berghei-infected mice showed an intense expression of NOS-2, no enzymatic expression was observed in retinal tissue of P. berghei-infected mice at 7 day post infection." (PMID 29096633, 2017). "Altogether, these results indicated that in the absence of type I IFN, DENV-ADE infection could impair the innate immune response through diminished NOS2 function." (PMID 26923481, 2016). "To investigate whether the enhanced viral production in DENV-ADE infected cells is the result of NOS2 functional suppression, we used cells pre-treated with the NOS2 specific inhibitor SMT at the concentrations of 0.1, 0.3, 0.5, and 1.0 μM before infection with DENV or the DENV-Ab complex." (PMID 26923481, 2016).